CCL2 (C-C motif chemokine ligand 2)
Diseases named in the same sentence as CCL2 in open-access papers (continued):
Sharing a sentence is not in itself a finding about the gene and the disease.
melanoma (continued). "The expression levels of CCL2 and HIF1A were positively correlated in BRAF-mutated melanoma tumor specimens, further supporting an association between HIF1 and CCL2." (PMID 26684239, 2016). "To assess the potential relevance of CCL2 in disease progression and in the response to BRAFi treatment in melanoma patients, we studied tumor samples and plasma in a set of cases with a follow-up of 2 y after the beginning of treatment with vemurafenib." (PMID 26684239, 2016). "Elevated levels of CCL2 have been reported in patients with breast, colorectal, prostate, melanoma, gastric and ovarian cancers, and was often correlated with disease progression." (PMID 26885690, 2016). "After exposure to PLX4032, both the transcript and the release of CCL2 were increased in most tested melanoma cell lines." (PMID 26684239, 2016). "Among the factors produced by PLX4032-resistant melanoma cell lines, CCL2 was higher compared to the sensitive parental cell lines and increased upon drug treatment." (PMID 26684239, 2016). "In order to confirm the impact of CatS on macrophage migration, B16 melanoma cells, which lack CCL2, were utilised and verified by ELISA." (PMID 26358505, 2015). "Quantitative FACS-based analysis confirmed the myeloid-cell-rich phenotype (Gr-1+/CD11b+ or CD11b+) of stably dedifferentiated syngeneic melanomas that also showed higher levels of Tnf and its downstream target Ccl2 as shown by ELISA assay of tissue lysates." (PMID 26530832, 2015). "In conclusion, our results showing that down-regulation of CCL2-driven signals via JNK contributes to reduce growth of melanoma cells provide a rationale for the therapeutic advantage of the combination of SAHA and TMZ." (PMID 24980831, 2014). "Because HDAC inhibitors are expected to act on transcription regulation, the modulation at the protein level in part reflected that of mRNA in tumors, as shown by TaqMan arrays; down-modulation of CCL2 was confirmed also in human melanoma cells." (PMID 24980831, 2014). "In the spontaneous ret transgenic mouse melanoma model, combination therapy produced a significant disease onset delay and down-regulation of Chemokine (C-C motif) ligand 2 (CCL2), JNK, and of Myeloid-derived suppressor cell recruitment." (PMID 24980831, 2014). "The STAT3 signaling pathway has been shown to be involved in the control of stemness and is activated by numerous cytokines present in the secretome of senescent melanoma, including CCL2." (PMID 24344100, 2013). "Tumor expression of the proinflammatory cytokine Ccl2, also called monocyte chemoattractant protein 1 (MCP1), has been associated with macrophage migration to the tumor and promotion of tumor growth in transplanted tumor models and human melanoma xenografts." (PMID 23173060, 2012). "In mouse tumor model systems, melanoma cells secreting high amounts of CCL2 attract macrophages resulting in inhibition of tumor growth." (PMID 21450101, 2011). "In mouse tumor model system, there are indications that melanoma cells secreting high amounts of CCL2 attract macrophages resulting in tumor growth inhibition." (PMID 21450101, 2011). "Key chemokines and cytokines, such as IL-1 beta, IL-8, IL-6 and CCL2/MCP1, were significantly upregulated in fibroblasts co-cultured with the invasive melanoma lines (BLM and MV3) compared to fibroblasts co-cultured with noninvasive (WM164) cells." (PMID 24212647, 2011). "Furthermore, our results suggest that inhibition cGAS activity and deletion of Cgas and Sting1 block mechanical force‐induced CCL2 production in melanoma VHPV metastasis, thereby attenuating splenic monocytes/macrophages infiltration in the liver." (PMID 39737867, 2025). "Furthermore, C5aR1 signaling induces the secretion of chemokine C-C motif ligand 2 (CCL2) by melanoma cells." (PMID 40370471, 2025). "We also detected CCL2 in melanoma tumours, consistent with an earlier observation." (PMID 38903497, 2024).
melanoma (continued). "Furthermore, we show that IFNγ stimulated dedifferentiated melanoma cells display increased secretion of CCL2, IL-10, CXCL10 and PD-L1 and increased PD-L1 expression on their cell membranes." (PMID 39736644, 2024). "CCL2 can mediate the invasiveness of metastatic melanoma cells." (PMID 38928238, 2024). "Indeed, we found that melanoma metastasis had high expression of CCL2, which increased following lung engraftment." (PMID 39545417, 2024). "S100A4 not only activates the nuclear factor‐kappa B (NF‐κB) pathway and leads to the release of the tumor necrosis factor (TNF)‐α, but also shapes an inflamed TME by inducing the secretion of IL‐8 and C—C chemokine ligand 2 (CCL2), playing an oncogenic role in malignant melanoma." (PMID 37414584, 2023). "Use of combination therapies, potentially including CDDO-Me, that target the CCL2/CCR2 axis may inhibit the development of treatment resistance in melanoma." (PMID 35265066, 2022). "The increase in CCL2, IL8, and CXCL1 was already observed in melanoma-associated fibroblasts." (PMID 35538545, 2022). "Upregulation of genes involved in macrophage recruitment (Ccl2), cell adhesion and migration (Vcam1, Stab1, Lyve1), angiogenesis (Vegfa) and cell proliferation/survival (Igf1) all suggested a phenotype similar to TAMs of s.c. melanoma." (PMID 36241867, 2022). "Also, chemokine (C-C motif) ligand 2 (CCL2) was downregulated which led to reduced MDSCs recruitment into the tumor site and contributed to reduced melanoma growth." (PMID 35140716, 2022). "Gabapentin may achieve anti-melanoma effects in mice by reducing cell proliferation, CCL2 production, and calcium influx." (PMID 35957907, 2022). "The fact that CCL2 is released by a compressed nerve —and, constitutively, by our melanoma cell line—may explain why 12 h after starting the gabapentin administration in the therapeutic protocol, a significant decrease in tumor size was observed." (PMID 34575835, 2021). "Properdin is a significant contributor to levels of C5a and CCL2 that are produced in this murine model of melanoma and may play a role in orchestrating immunosuppressive cells in the tumour microenvironment and periphery." (PMID 33494138, 2021). "Analyzing several melanoma cell lines resistant to BRAFi as well as plasma and tumor samples from vemurafenib-treated melanoma patients, Vergani and coauthors found that BRAFi-resistant melanoma cells secrete higher levels of CC-chemokine ligand 2 (CCL2) then sensible counterparts." (PMID 32604720, 2020). "Increasing studies indicated that inhibition of CCL2 could deplete inflammatory monocytes and macrophages, reduce tumor growth and dissemination in different experimental models such as prostate, melanoma, breast, lung and liver cancer." (PMID 32103760, 2020). "In melanomas, the chemokines CCL-2, CCL-3, CCL-5, CXCL-9, and CXCL-10 recruit CD8+ T cells." (PMID 31134198, 2019). "Furthermore, analysis of chemokines in melanoma prior to treatment identified CCL2 and CXCL9-12 as elevated in responding patients compared to non-responding patients." (PMID 30899263, 2019). "Similarly, an increase in the serum levels of CCL2 occurs in melanoma patients after extended vemurafenib treatment, and is associated with a poor clinical response." (PMID 31762942, 2019). "Taken together these results suggested that CCL2 could be viewed as a potential prognostic factor and an index for resistance to therapy in patients with melanoma." (PMID 31762942, 2019). "Furthermore, expression of CCL2 in human IIB-MEL-J melanoma increased intra-tumor macrophage infiltration and tumor growth while macrophage-depleted mice developed smaller tumors." (PMID 30899263, 2019). "Another study in BRAF V600E mouse melanoma transplants and in de novo melanomas demonstrated that BRAF inhibitor downregulated tumor expression of chemokine (C-C motif) ligand 2 (CCL2), and resulted in a robust increase in CD8+ T/FoxP3+CD4+ T cell ratio and natural killer (NK) cells." (PMID 29156850, 2017).
melanoma (continued). "RNA in situ hybridization confirmed the expression of CCL2 transcript in melanoma cells." (PMID 26684239, 2016). "In melanoma, it has been demonstrated that up regulation of expression of several chemokine genes such as Ccl2, Ccl3, Ccl4, Ccl5, Cxcl9, and Cxcl10 in the tumor microenvironment correlates with the recruitment of activated effector T cells to the tumor increasing antitumor immunity." (PMID 27876058, 2016). "The identification of a UV-miRNA-regulated network that inter-connects with a number of de-repressed genes (e.g. PD-L1 and CCL2) involved in immune evasion in the melanocytes of melanoma patients was unexpected, and to the best of our knowledge, the first evidence of its kind." (PMID 27149382, 2016). "Although we did not document M2 polarization of TAMs in our model, our results could be consistent with models in which CCL2 expression drives M2 polarization of TAMs in melanoma xenografts and in human peripheral blood mononuclear cells." (PMID 27820834, 2016). "Finally, the SASP factor MCP-1 (CCL2), found in the conditioned media of senescent melanoma cells, was demonstrated to promote DNA lesions in other cells, as illustrated by an increase in 53BP1 DDF." (PMID 25815006, 2015). "Furthermore, the monocyte chemoattractant protein-1 (CCL2) gene was found to be activated in melanoma cells during exposure to hypoxia and the reoxygenation process." (PMID 26703734, 2015). "When we treated human melanoma cells with recombinant-CCL2, we observed that the chemokine could trigger JNK activation as phosphorylation of JNK1/2 was found." (PMID 24980831, 2014). "In cultured murine melanoma cells, we found that CCL2 was released in the medium suggesting that it is produced by cells and it might act in sustaining survival by autocrine/paracrine mechanisms in the tumor microenvironment." (PMID 24980831, 2014). "In addition, DC pulsed with reovirus-infected melanoma cells secrete the chemokines CCL2, 3, 4, 5, 7, 8, 11 (eotaxin), and CXCL10 (IP-10), and these culture supernatants induce NK cell chemotaxis." (PMID 21338484, 2011). "The chemokine CCL2, known to be involved in tumor progression and metastasis, has been studied as well, demonstrating that BRAF-targeted therapy decreases CCL2 gene expression and secretion, correlated with reduction in tumor size in a specific murine model of BRAF-mutated melanoma." (PMID 40872623, 2025). "Furthermore, the results suggest that a subgroup of dedifferentiated melanoma cells expresses increased levels of PD-L1, CCL2 and IL-8 in response to IFNγ, with IRF1 expression contributing highly to the upregulated inflammatory signaling responses of PD-L1high expressing cells." (PMID 39736644, 2024). "Dedifferentiation renders 624Mel melanoma cells hypersensitive to IFNγ stimulation in a context-dependent manner, resulting in non-additive upregulation of IFNγ-induced genes, increased PD-L1 protein expression and amplified secretion of CCL2, CXCL10 and IL-10." (PMID 39736644, 2024). "In addition to its direct effects on melanoma cell development and progression, CCL2 also plays a vital role in the recruitment of immune cells, such as MDSCs and monocytes, which differentiate into TAMs to initiate a microenvironment conducive to tumour cell proliferation." (PMID 37170733, 2023). "Additionally, melanoma cell-derived sEVs modulate bone marrow-derived MSCs (BM-MSCs) phenotype for the production of large amounts of macrophage-recruiting chemokines such as chemokine (C-C motif) ligand 2 (CCL2) and CCL7." (PMID 36704194, 2022). "We found that B16–BL6/Zs green melanoma cells secrete CCL2 spontaneously; thus, the tumor mass could directly affect the excitability of nociceptive neurons in our animals, and might induce the upregulation of CCL2 receptors (CCR2 and CCR4), as has been previously suggested." (PMID 34575835, 2021). "Therefore, CCR2b could be applied to enhance CAR-T migration in high-CCL2-expressing tumors, such as neuroblastoma and melanoma." (PMID 34778046, 2021).
melanoma (continued). "As both melanoma cells and macrophages exposed to supernatants from bcl-2-overexpressing cells expressed higher levels of the receptors for IL-1β, IL-17, IL-8 and CCL2, it is conceivable that these cytokines may critically support an active interplay between the tumoral and stromal compartments." (PMID 32269145, 2020). "sEVs of hypoxic melanoma, squamous skin carcinoma and lung cancer cells are loaded with immunosuppressive proteins like colony-stimulating factor 1 (CSF-1), C-C motif chemokine 2 (CCL2), ferritin heavy chain (FTH), ferritin light chain (FTL) and TGF-β as well as the miRNA let-7a." (PMID 32709110, 2020). "Similarly, Roccaro and colleagues demonstrated that EVs from bone marrow mesenchymal stem cells transfer several cytokines, such as IL6, CCL2 (also known as MCP1), and junction plakoglobin (also known as γ-catenin), on melanoma cells, promoting tumor growth both on in vitro and in vivo models." (PMID 30532788, 2018). "Moreover, macrophages are a major source of CCL2, CCL3, CCL4, CCL5, CXCL9 and CXCL10, which are important chemokines that induce T lymphocyte chemotaxis, and which we find in association with stromal activation in actual melanomas." (PMID 28448494, 2017). "Thus, the combination, while being therapeutically effective by improving disease free-survival could provide an approach to impair CCL2 production, an effect that may be exploited in the clinical setting to control melanoma growth." (PMID 24980831, 2014). "In the Yummer B2M KO melanomas, with relatively lesser TAM infiltration, compared to MC38 B2M KO tumors, a robust induction of CCL2 is observed along with a significant increase in TAM numbers." (PMID 40560386, 2025). "Melanoma-derived fibroblasts secrete factors such as C–C motif chemokine ligand 5 (CCL5), CCL2, and C-X-C motif chemokine ligand 12 (CXCL12), which induce immune checkpoint (ICP) ligand expression in melanoma cells, thereby compromising CD8+ T cell function." (PMID 40399946, 2025). "On the other hand, CCL2-induced macrophages are known to produce VEGF-A and activate the AKT signaling pathway to increase STC1 expression in melanoma, thereby contributing to YAP activation and subsequent CCL2 upregulation." (PMID 40380196, 2025). "The influx of macrophages prompts melanoma cells to secrete angiogenic factors like VEGF and pro-inflammatory cytokines such as MCSF (Macrophage colony-stimulating factor) and CCL2." (PMID 40399946, 2025). "NF-κB also appears to be responsible for much of the basal expression of CCL2, CCL5, and TNF, possibly a consequence of upregulated NF-κB activity, a common feature of melanoma." (PMID 40507298, 2025). "These included Il10, Ccl2, and Cxcl2, which are also up-regulated in response to SHP2 inhibition in melanoma." (PMID 40992926, 2025). "CCL2-stimulated macrophages produce VEGF-A and activate the AKT signaling pathway, leading to upregulation of STC1 in melanoma models, which in turn promotes YAP activation and further amplifies CCL2 expression." (PMID 41417432, 2025). "We postulate that the classical CD16− monocytes are recruited into the melanoma TME, likely via tumour-derived CCL2, where they upregulate CD163 and gradually lose the expression of CD14 and CCR2." (PMID 38903497, 2024). "Cytokine array from SSM2c cells transduced with LV-c or LV-shGLI1 showed a significantly higher secretion of CCL7, CCL2, CCL20 and CXCL8 (IL-8) in CM collected from GLI1-silenced melanoma cells." (PMID 39090759, 2024). "Increased levels of CCL2 (C-C motif chemokine ligand 2), serpine E1, and IL6 cytokines were observed in both resistant melanoma cell lines." (PMID 39175042, 2024). "Overexpression of GLI1 in A375 melanoma cells drastically downregulated CCL7, CCL2, CCL20 and CXCL8 mRNA level." (PMID 39090759, 2024). "In the secretomes of MITF-silenced senescent melanoma cells, E-cadherin was reduced and CCL2 (Chemokine (C-C motif) ligand 2) was significantly increased." (PMID 37174106, 2023).
melanoma (continued). "Adipocytes cocultured with melanoma cells secreted higher IL6 and SerpinE1 levels and produced less CCL2, CXCL1, and angiogenic molecules." (PMID 37481560, 2023). "The major chemokine/chemokine receptor interactions occurring in melanoma development and progression include the CXCR4/CXCR7/CXCL12, CXCR3/CXCL9,10,11, CXCR1,2/CXCL8, CCR2/CCL2, CCR4/CCL17,22, CCR5/CCL5, CCR7/CCL21 and CCR10/CCL27 axes." (PMID 37170733, 2023). "Fibroblasts in the blood can recruit MDSCs by secreting CCL2, which also promotes the establishment of lung PMN and lung metastasis of melanoma cells." (PMID 37056561, 2023). "Studies have shown that WNT5A regulates IL-6 expression in melanoma and modulates the expression of SASP factors in tendon stem cells, and that IL-6 exhibits a reciprocal regulation with CCL2 in non–small cell lung cancer." (PMID 37607007, 2023). "Monoculture CCL2 and IL-6 levels were measured to assess SK-MEL-28 vs. melanoma-conditioned macrophage protein production." (PMID 35265066, 2022). "The secretion of CCL2, which was induced in SK-MEL-28 melanoma cells, contributes to the clearance of senescent tumor cells in hepatocellular carcinoma through the recruitment of myeloid cells." (PMID 35563820, 2022). "In melanoma, a pro-inflammatory phenotype is induced in astrocytes exposed to melanoma exosomes that included the upregulation of IL-1α, IL-1β, CXCL1 and CCL2 among others." (PMID 36704194, 2022). "The therapeutic block of the CCL2/CCR2 axis has yielded promising results to slow the progression of several tumor types; the therapy of melanoma-targeting CCR2 inhibited tumor growth in laboratory animals." (PMID 35269787, 2022). "The chemokine ligand CCL2 or monocyte chemoattractant protein 1 (MCP-1) mediates the trafficking of immune cells into the TME in many types of malignancies, such as melanoma, colorectal, breast, prostate and pancreatic cancer." (PMID 35211124, 2022). "Basing on this finding, we postulate that CCL2 and VEGF-A are liberated from the melanoma cell produced extracellular matrix." (PMID 33920100, 2021). "Studies using a melanoma brain metastasis immunocompetent mouse model revealed an upregulation in proinflammatory cytokines CXCL10, CCL17, CCL2, IL6, and IL-1β." (PMID 33466236, 2021). "The analysis of the melanoma cell secretome indicated that CHI3L1 increases the abundance of various cytokines, such as CC-chemokine ligand 2 (CCL2), and growth factors, such as vascular endothelial growth factor A (VEGF-A)." (PMID 33920100, 2021). "Using qRT-PCR we observed an increased expression of IL-1β, CCL1, CCL2, and CD80 in transfected M1 macrophages, similarly to in M1 macrophages co-cultured with melanoma cells or treated with melanoma-derived exosomes." (PMID 32079286, 2020). "As we showed, melanoma exosome-delivered miR-125b-5p reinforces the activation of M1 macrophages through the induction of CCL1, CCL2, and IL-1β expression, thus contributing to myeloid cell recruitment and cancer-associated inflammation." (PMID 32079286, 2020). "In an in vitro model aiming to mimic ILP, we observed that melphalan exposure triggered a pronounced induction of CXCL10, CCL2 and IFN-γ in melanoma/PBMC co-cultures." (PMID 32002296, 2020). "Similar to what was observed in cell lines, miR-146a expression levels were inversely correlated with the levels of its target genes EGFR, CCL2 and BCL2L1 in melanoma metastases." (PMID 32967672, 2020). "Peripheral blood mononuclear cells (PBMCs) secreted high levels of CXCL10, CCL2 and IFN-γ in response to co-culture with melphalan-exposed melanoma cells in vitro." (PMID 32002296, 2020). "We had access to melanoma tumors from patients obtained prior to ILP and observed a positive correlation between intratumoral CCL2 levels and CD8+ T cell content." (PMID 32002296, 2020).